OTUD4 (OTU deubiquitinase 4)
Diseases named in the same sentence as OTUD4 in open-access papers (continued):
Sharing a sentence is not in itself a finding about the gene and the disease.
glioma (2 papers, 2024 to 2025). A benign or malignant brain and spinal cord tumor that arises from glial cells (astrocytes, oligodendrocytes, ependymal cells). "Consistent with the database results, immunohistochemical staining on tissue samples from glioma patients showed that the expression level of OTUD4 was significantly increased in glioma, especially in grade 4 tissues." (PMID 38429268, 2024). "Meanwhile, OTUD4 has the highest expression in GBM (the top level of glioma), and the increase of OTUD4 gene copy number was significantly correlated with its expression level in glioma." (PMID 38429268, 2024).
autoimmune disease (1 paper, 2025). A disorder resulting from loss of function or tissue destruction of an organ or multiple organs, arising from humoral or cellular immune responses of the individual to their own tissue constituents. "We found that OTUDs can inhibit the RNA virus-induced innate immune response process to prevent the development of autoimmune diseases, while the role of OTUD4 is still controversial." (PMID 41050073, 2025).
colon cancer (1 paper, 2023). "A thorough understanding of the role of OTUD4 in different types of cells during colon cancer development requires comprehensive studies in the future." (PMID 37193092, 2023). "We next investigated the role of OTUD4 in colon cancer development." (PMID 37193092, 2023). "However, knockout of OTUD4 had minimal effects on colon cancer development in the AOM/DSS model or the AOM/VP model." (PMID 37193092, 2023).
emphysema (1 paper, 2023). "Overall, these findings revealed that OTUD4 play a potential role in protecting CSE- induced emphysema in mice by decreasing cell apoptosis." (PMID 37726265, 2023). "Restoration of OTUD4 in mice mitigated lung cell apoptosis, thus contributed to the alleviation of emphysema morphology change in COPD." (PMID 37726265, 2023). "Interestingly, the OTUD4 expression was obvious reduced in the lung tissue of cigarette smoke extract induced emphysema mouse model." (PMID 37726265, 2023). "We confirm that OTUD4 was successfully overexpressed in CSE induced emphysema mice." (PMID 37726265, 2023). "However, the treatment of tiplaxtinin can inhibit the protective effect of OTUD4 in CSE induced emphysema." (PMID 37726265, 2023). "In our research, we also found that de-ubiquitination enzyme OTUD4 decreased in CSE-treated bronchial epithelial cell and emphysema mouse model, which is suggested to involved in COPD pathogenesis." (PMID 37726265, 2023). "What’s more, the morphological indexes of emphysema including MLI and DI were decreased after OTUD4 upregulation (lower two panels)." (PMID 37726265, 2023). "Interesting, in situ TUNEL assay confirmed that lack of OTUD4 enhanced the cell apoptosis in the lung tissue of CSE induced emphysema model." (PMID 37726265, 2023). "Furthermore, the morphological indexes of emphysema including MLI and DI were dramatically increased following the reduction of OTUD4." (PMID 37726265, 2023). "However, whether restoring the OTUD4 could protect the mice from emphysema damage is not clear." (PMID 37726265, 2023).
herpesvirus infection (1 paper, 2024). "Interestingly, A recent study shows that HSV-1 ICP0 interacts with OTUD4, suggesting that OTUD4 is involved in herpesvirus infection." (PMID 38215174, 2024).
lung adenocarcinoma (1 paper, 2019). A carcinoma that arises from the lung and is characterized by the presence of malignant glandular epithelial cells. "Analysis of TCGA dataset showed that OTUD4 level was significantly depressed in both lung adenocarcinoma (LUAD) and squamous cell carcinoma (LUSC) tissues compared with normal lung tissues." (PMID 31011293, 2019).
neuroblastoma (1 paper, 2019). Neuroblastoma (NB) is the most common solid, extracranial childhood tumor. "In contrast, neuroblastoma SH-SY5Y cells depleted of OTUD4 showed a much stronger activation of caspase-3 in response to arsenite treatment compared to control cells." (PMID 31138677, 2019).
pheochromocytoma (1 paper, 2025). "Of particular interest, the naturally occurring OTUD4 missense variant H148Y (c.442C>T, p.H148Y), identified in pheochromocytomas, resides within the catalytically essential His loop of the OTU domain, suggesting functional impairment." (PMID 41062071, 2025). "To assess the functional impact of a tumor-associated DUB variant, we examined the OTUD4 H148Y missense variant (c.442C>T, p.H148Y), cataloged in COSMIC (ID: COSP38343) and initially reported in pheochromocytoma." (PMID 41062071, 2025).
primary effusion lymphoma (1 paper, 2024). A large B-cell lymphoma located in the body cavities, characterized by pleural, peritoneal, and pericardial fluid lymphomatous effusions and that is always associated with human herpes virus-8 (HHV-8). "Next, we used BCBL-1-Tet-K-RTA, a human primary effusion lymphoma (PEL) cell line that initiates lytic reactivation upon doxycycline induction, and confirmed that knockdown of OTUD4 greatly impaired KSHV lytic replication." (PMID 38215174, 2024).
prostate carcinoma (1 paper, 2026). A carcinoma that arises from epithelial cells of the prostate gland. "Although previous studies have shown that the expression and function of OTUD4 vary across different tumors, its role in prostate cancer remains unknown." (PMID 41930143, 2026). "Specifically, OTUD4 inhibits MYH9 degradation via deubiquitination, thereby enabling MYH9-mediated suppression of prostate cancer." (PMID 41930143, 2026).
testicular germ cell tumours (1 paper, 2020). "Interestingly, in all but one of these tumour types OTUD4 expression positively correlated with TGFβ activation, whilst only in testicular germ cell tumours (TGCT) was OTUD4 expression negatively correlated with TGFβ activity." (PMID 32973272, 2020).
thyroid cancer (1 paper, 2021). "OTUD4 is the fifth frequently mutated gene in thyroid cancer, and its mutation rate in the thyroid is 2%." (PMID 34493981, 2021).
ulcerative colitis (1 paper, 2023). An inflammatory bowel disease involving the mucosal surface of the large intestine and rectum. "OTUD4 is upregulated in the inflamed mucosa of ulcerative colitis patients and in the colon of mice treated with dextran sulfate sodium salt (DSS)." (PMID 37193092, 2023).
ZIKV infection (1 paper, 2022). "The predicated target gene OTU deubiquitinase (DUB) 4 (OTUD4) was over-expressed by plasmid transfection or silenced by siRNA transfection into cells prior to ZIKV infection." (PMID 35317262, 2022). "Furthermore, to determine whether OTUD4 could counteract the pro-viral effect of miR-103a-3p on ZIKV replication, we co-transfected miR-103a-3p and OTUD4 plasmid into A549 cells in the presence of ZIKV infection." (PMID 35317262, 2022). "Zika virus infection induced the expression of miR-103a-3p, which subsequently activated p38 MAPK signaling pathway by targeting OTUD4 to facilitate ZIKV replication." (PMID 35317262, 2022). "In summary, data from our current study indicated that ZIKV infection induced miR-103a-3p upregulation, which in turn was exploited by ZIKV to promote its own replication through targeting OTUD4 to activate p38 MAPK signaling pathway." (PMID 35317262, 2022). "Transfection of OTUD4 plasmid led to a remarkable upregulation of OTUD4 mRNA and protein expression in A549 cells with or without ZIKV infection." (PMID 35317262, 2022). "We also observed decreased phosphorylation of p38 MAPK and HSP27 in OTUD4 over-expressed cells, while increased in OTUD4 silenced cells in the presence or absence of ZIKV infection." (PMID 35317262, 2022). "MiR-103a-3p stimulates ZIKV replication by targeting OTUD4 to activate the p38 MAPK signaling pathway and targeting miR-103a-3p or p38 MAPK signaling may provide a viable approach for the treatment of ZIKV infection." (PMID 35317262, 2022). "OTUD4 siRNA could efficiently suppress its mRNA and protein expression in A549 cells in the presence or absence of ZIKV infection." (PMID 35317262, 2022).
tumor (17 papers, 2019 to 2026). "This function requires a catalytic His loop and is disrupted by the tumor-associated H148Y substitution, linking impaired OTUD4 catalysis to persistent proinflammatory signaling." (PMID 41062071, 2025). "Disruption of this loop, modeled by the tumor-associated H148Y variant, abolishes intrinsic activity toward both K63- and K48-linked chains, thus providing a direct link between OTUD4 catalytic failure and persistent proinflammatory signaling." (PMID 41062071, 2025). "The underlying details of interplay between TRIM21 and OTUD4 in determining cellular CD73 abundance modulating tumor immune responses in the context of tumor progression awaits further investigation." (PMID 38530357, 2024). "For instance, OTUB1 promoted NPC progression by regulating ferroptosis and radioresistance, while OTUD3 and OTUD4 impaired anti-tumor immune responses by stabilizing PD-L1 and CD73, respectively." (PMID 40469292, 2025). "Studies have shown that as a tumor suppressor, OTUD4 expression is significantly down-regulated in various solid tumors, and low OTUD4 expression is a predictive molecule for poor prognosis." (PMID 41050073, 2025). "Together, these results indicate that the His loop, disrupted by the tumor-associated H148Y variant, functions independently of UIM binding and Ser202 phosphorylation to regulate intrinsic OTUD4 catalytic activity across linkage types." (PMID 41062071, 2025). "The combination of ST80 with anti-PD-L1 therapy significantly enhanced the therapeutic efficacy against TNBC tumors, effectively inhibiting tumor growth even in cases with high expression of OTUD4 and CD73." (PMID 40867511, 2025). "CD 73 is an immune checkpoint enzyme in cancer that promotes tumour aggression by suppressing the recruitment of leukocytes to the tumour but can be stabilised by the deubiquitinating enzyme OTUD4." (PMID 40092697, 2025). "Modulation of CD73 proteolysis by OTUD4 affects tumor growth and capacity to elicit antitumor CD8+ T cell responses." (PMID 38530357, 2024). "The upregulation of TGF-β (commonly found in a tumor microenvironment) coopted OTUD4 to deubiquitylate CD73 hyperactively, potentiating its stability and membrane abundance, immune evasion, and maintaining tumor progression." (PMID 38747288, 2024). "Development of a pharmacological inhibitor that blocks OTUD4/CD73 interaction in restoring tumor immune responses in immune-suppressive TNBCs." (PMID 38530357, 2024). "We further revealed a role of TGF-β signaling in orchestrating the OTUD4/CD73 proteolytic axis that promotes tumor progression." (PMID 38530357, 2024). "To analyze the affect of OTUD4 in modulating tumor immunity, we examined the tumor immune infiltrates using a high-dimensional spectral flow cytometry (CyTEK) panel that incorporated hallmark markers for all major immune populations." (PMID 38530357, 2024). "To evaluate the role of OTUD4 in tumor growth in vivo, we created murine cell lines with modified OTUD4 expression." (PMID 38530357, 2024). "We further demonstrated the importance of TGF-β signaling for orchestrating the OTUD4/CD73 proteolytic axis within tumor cells." (PMID 38530357, 2024). "In summary, this study reveals what we believe to be a previously unidentified role for the OTUD4/CD73 proteolytic axis in determining tumor immune evasion in TNBC." (PMID 38530357, 2024). "The H&E results found that the tumor growth capability of GBM cells was significantly decreased after OTUD4 knockdown." (PMID 38429268, 2024).
tumor (continued). "We also found that OTUD4 OE in tumor cells enhanced a tumor-promoting M2-like phenotype in TAMs, usually defined by the expression of CD163." (PMID 38530357, 2024). "IHC experiments displayed that the positive expressions of Ki67(a well-known marker of cell proliferation), OTUD4, CDK1, FGFR1 and p-BRAF were obviously decreased in tumor xenografts with OTUD4 knockdown." (PMID 38429268, 2024). "T cell proliferation activity and IFN-γ production were elevated when OTUD4 was knocked down in tumor cells, whereas OTUD4 overexpression in tumor cells led to a decrease in T cell proliferation activity and IFN-γ production." (PMID 38530357, 2024). "We next aimed to determine the therapeutic consequence of blocking the OTUD4/CD73 complex formation toward restoring tumor immune response in immune-suppressive TNBCs." (PMID 38530357, 2024). "Ovarian tumor family deubiquitinase 4 (OTUD4) belongs to the ovarian tumor proteases (OTUs) DUB family and is implicated to cleaves K48- and K63- linked poly ubiquitin chains." (PMID 37726265, 2023). "Recently, OTUD4 has been identified to be down-regulated in multiple human tumor types, and lower OTUD4 expression indicates a poor prognosis." (PMID 36411454, 2022). "In vitro and in vivo assays were used to investigate the function of gasdermin E (GSDME) and ovarian tumor family deubiquitinase 4 (OTUD4)." (PMID 36411454, 2022). "More importantly, patients with low OTUD4 expression (biopsy III, IV) showed a lower level of GSDME, no significant upward trend of serum LDH concentration and a slower regression of the tumor than patients with high OTUD4 expression (biopsy I, II)." (PMID 36411454, 2022). "Taken together these results suggests that OTUD4 is an integral regulator of the TGFβ pathway in multiple tumour types." (PMID 32973272, 2020). "Our results suggest a tumor-suppressing function of OTUD4 and prove OTUD4 to be a potential target for radiosensitizing NSCLC." (PMID 31011293, 2019). "MSP assay showed that OTUD4 promoter genomic DNA was largely methylated in tumor tissues form 10 NSCLC patients." (PMID 31011293, 2019). "This study uncovers a tumor-suppressing role of OTUD4 and that OTUD4 is a potential radiosensitizer for NSCLC." (PMID 31011293, 2019). "The data support a tumor-promoting role of the OTUD4/CD73 proteolytic axis in vivo." (PMID 38530357, 2024). "Nevertheless, the impact of OTUD4 in regulating tumor immune response and tumor progression remains largely unknown." (PMID 38530357, 2024). "The results underscore the importance of OTUD4-mediated deubiquitylation of CD73 for tumor growth." (PMID 38530357, 2024). "Furthermore, OTUD4 overexpression resulted in an increase in membrane-bound expression levels of CD73 on tumor cells from tumor-bearing mice." (PMID 38530357, 2024). "Interestingly, there was no change in OTUD4 protein levels in MDA-MB468-ShTRIM21 cells with IFN-γ treatment, suggesting little contribution of IFN-γ to affect OTUD4 activity in tumor cells." (PMID 38530357, 2024). "Moreover, knockdown of OTUD4 significantly increased the sensitivity of PC-3 and H23 tumor cells to methyl methanesulfonate, an alkylating agent which leads to DNA alkylation damage." (PMID 31011293, 2019). "Collectively, these results demonstrate that OTUD4 suppresses TNF-induced NF-κB signaling by removing K63-linked Ub chains from the TAK1 signalosome, a function that depends on intrinsic catalytic activity and is abolished by the tumor-associated H148Y variant." (PMID 41062071, 2025). "Together, these results demonstrate that OTUD4 suppresses TAK1 signaling by directly removing K63-linked polyubiquitin chains, a function requiring an intrinsic catalytic activity, mediated by the His loop, that is abolished by the tumor-associated H148Y variant." (PMID 41062071, 2025).
tumor (continued). "Our data indicated that OTUD4 is associated with PAI-1, a serine protease inhibitor (SERPIN), which is related to ubiquitin proteasome degradation in the regulating of cell death and was reported to promote angiogenesis and tumor cell survival by preventing apoptosis." (PMID 37726265, 2023). "Furthermore, IHC displayed higher GSDME protein levels in OTUD4-overexpressing tumor xenografts." (PMID 36411454, 2022). "In addition, OTUD4 is involved in the repair of DNA alkylation damage, and OTUD4 deletion increased the sensitivity of tumor cells to alkylating agents, suggesting that OTUD4 may be a novel target for enhancing the sensitivity of tumor cells to alkylating drugs." (PMID 41050073, 2025). "The study revealed that OTUD4 stabilizes CD73 through deubiquitination, thereby suppressing the cytotoxic function of CD8+ T cells and promoting tumor immune escape." (PMID 40867511, 2025). "To evaluate the importance of the physical interaction between OTUD4 and CD73 for tumor growth, we overexpressed both OTUD4 and CD73WT (OTUD4 OE + CD73WT) or OTUD4 and CD73V300P/I301Q with mutated interaction sites (OTUD4 OE + CD73V300P/I301Q) in EO771 cells." (PMID 38530357, 2024). "Mechanistically, transforming growth factor-β (TGF-β) signaling orchestrated the OTUD4/CD73 proteolytic axis, promoting tumor progression." (PMID 38747288, 2024). "Mechanistically, deubiquitylation of CD73 by OTUD4 counteracted its ubiquitylation by TRIM21, resulting in CD73 stabilization inhibiting tumor immune responses." (PMID 38530357, 2024). "Mechanistically, we have demonstrated that stabilization of CD73 catalyzed by OTUD4 suppresses cytotoxic CD8+ T cell function, leading to tumor immune evasion." (PMID 38530357, 2024). "Further, our GSEA analyses showed correlation between high OTUD4 expression and increased TGF-β signaling activity, implying a cascade of TGF-β/OTUD4/CD73 in maintaining a tumor-promoting immune microenvironment." (PMID 38530357, 2024). "Hijack of OTUD4 by TGF-β antagonizes IFN-γ/TRIM21 cascade, stabilizing CD73 and inhibiting tumor immunogenicity." (PMID 38530357, 2024). "OTUD4-mediated stabilization of CD73 suppressed cytotoxic CD8+ T cell function, thereby facilitating tumor immune destruction." (PMID 38747288, 2024). "Increased CD73 deubiquitylation by OTUD4 due to etiological factors enhances function for membrane-bound CD73, conferring tumor immune evasion." (PMID 38530357, 2024). "We observed a positive correlation between OTUD4 and CD73 expression in malignant epithelial areas across all regions per tumor." (PMID 38530357, 2024). "The data together support a great potential of pharmacological targeting of the proteolytic interaction of OTUD4 and CD73 to mitigate tumor immune evasion and revive antitumor T cell immunity." (PMID 38530357, 2024). "In this study, we found that OTUD4 was significantly downregulated in NSCLC cell lines and tumor tissues compared with normal controls." (PMID 31011293, 2019). "OTUD4 was dramatically downregulated in NSCLC cell lines and tumor tissues compared with the lung bronchus epithelial cell BEAS-2B cells and the matched adjacent non-tumor tissues respectively in both protein and RNA level." (PMID 31011293, 2019). "Targeting a specific interaction between tumor OTUD4 and CD73 to efficiently destabilize CD73 is an effective strategy for TNBC treatment, especially when combined with PD-L1 blockade, even in the case with abundant expression of tumor CD73 and OTUD4." (PMID 38530357, 2024). "To validate the spatially correlated expression of OTUD4 and CD73 in tumor cells with immune signaling programs in the tumor microenvironment, we performed spatially indexed transcript profiling (GeoMx digital spatial profiling) of tumor tissue sections from 6 patients with TNBC." (PMID 38530357, 2024). "In vivo experiments showed that upregulating OTUD4 or silencing GSDME did not significantly affect xenograft tumor growth without ionizing radiation." (PMID 36411454, 2022).